LOX (lysyl oxidase)
Diseases named in the same sentence as LOX in open-access papers (continued):
Sharing a sentence is not in itself a finding about the gene and the disease.
breast carcinoma (continued). "However, in breast cancer, elevated LOX expression has been positively-correlated with migration and invasion." (PMID 23545606, 2013). "Furthermore, overexpression of LOX in poorly invasive breast cancer cell lines results in an increase in in vitro migration and invasion." (PMID 23545606, 2013). "For example, LOX-PP reverts the invasive phenotype of breast cancer cells, inhibits the transformed phenotype of lung and pancreatic cancer cells, interferes with FAK activation in breast cancer cells and inhibits prostate cancer cell growth by targeting FGF-2 cell binding and signalling." (PMID 23750284, 2013). "LOX was identified to be upregulated in breast cancer cells with metastatic ability and to facilitate breast cancer cell migration and adhesion through the hydrogen peroxide-mediated regulation of the FAK/Src signaling pathway leading to downstream changes in cell adhesion and migration." (PMID 23425977, 2013). "We recently noted that LOX-PP can physically interact with c-Raf and Hsp70 in breast cancer cells." (PMID 22438909, 2012). "Since HIF-regulation of lysyl oxidase (LOX) was required for hypoxia-induced migration of breast cancer cells, we investigated whether lysyl oxidases were involved in mediating the EMT-promoting effects of hypoxia in PTECs." (PMID 23259746, 2012). "Furthermore, treatment with a LOX inhibitor reduced tumor growth in the MMTV-neu breast cancer model." (PMID 22509805, 2012). "LOX up-regulation has been correlated with a worse prognosis breast cancer, thus, in addition to its induction during hypoxia, it has been proposed that LOX might be required for the growth of already established metastases." (PMID 19440335, 2009). "Both up- and down-regulation of LOX has been observed in different cancer cell lines and primary tumors, however, in breast cancer, elevated LOX expression has been positively-correlated with invasiveness, as well as with reduced metastasis-free and overall survival." (PMID 19440335, 2009). "In addition, increased LOX expression has been correlated with decreases in both metastases-free, and overall survival in breast cancer patients." (PMID 19440335, 2009). "However, the role of LOX is cancer biology is complex as LOX has also been shown to enhance breast cancer cell migration." (PMID 18828910, 2008). "The LOX [GenBank:NM_002317] gene mediates metastasis of human breast cancer cells in a mouse model and regulates in vitro breast cancer cell migration and cell-matrix adhesion through the regulation of Scr kinases and FAK, making it a candidate for predicting progression of DCIS." (PMID 18928525, 2008). "Moreover, coupled with the associations in this review linking collagen, LOX, and MMP upregulation with breast cancer, these results indicate the potential for GLP-1 agonist incorporation into combinatorial regimens as a therapeutic strategy for breast cancer in obese patients." (PMID 40847127, 2025). "In addition, epigenetic regulation of LOX plays an important role in tumor progression; for instance, LOX derived from M2-like macrophages promoted breast cancer cell migration and collagen crosslinking, and this phenomenon was suppressed by an H3K27 demethylase inhibitor." (PMID 38246995, 2024). "The depletion of copper LOX catalytic sites in the nonspecific copper chelator tetraithiomolybdate reduced the serum LOXL2 concentration in patients with moderate- to high-risk primary breast cancer in a phase II clinical trial (NCT00195091)." (PMID 39697341, 2024). "In murine breast cancer cells, LOX-PP similarly inhibited FGF2 stimulated proliferation and signaling in vitro and xenograft growth in mice, while the Arg152Gln rat variant did not inhibit signaling and inhibited xenograft growth to a lesser degree than Arg152 LOX-PP." (PMID 35563478, 2022).
breast carcinoma (continued). "In vitro, cancer cell-intrinsic LOX-PP expression inhibited the proliferation and invasion of prostate, pancreatic, and mammary carcinoma cells, and suppressed signaling pathways downstream of oncogenic Her2/Neu (breast cancer) and Ras (prostate and pancreatic cancer)." (PMID 35804902, 2022). "The LOX pro-peptide has been shown to reduce the invasive phenotype and anchorage independent growth of Ras transformed lung cancer, pancreatic cancer, breast cancer and fibroblasts on soft agar and reduce expression and binding of Ras stimulated NF-κB, whereas mature LOX had the opposite effect." (PMID 33513979, 2021). "Indeed, Rachman-Tzemah and collaborators show that, in breast cancer, surgery-induced hypoxia promotes LOX secretion that, by enhancing fibrillary collagen crosslinking and focal adhesion signaling pathway, favors metastasis development and decreases mouse survival." (PMID 34298680, 2021). "Moreover, inhibition of LOX was demonstrated to lead to a decrease in collagen crosslinking and subsequently a reduction in the generation of the insoluble fibrotic matrix, thus preventing breast cancer metastasis." (PMID 35006432, 2021). "However, LOX knockdown also leads to increased levels of the proangiogenic factors (VEGF, PDGF‐AA, and GM‐CSF), which may increase the risk of breast cancer progression." (PMID 34617419, 2021). "Moreover, higher LOX expression was observed in metastatic brain tumors of breast cancer patients." (PMID 32415208, 2020). "However, it is still unclear whether hypoxia induced LOX is critical for breast cancer lung metastasis and how LOX inhibition affects pre-metastatic niche formation in the lung tissue." (PMID 30181809, 2018). "In this landmark study, LOX secreting 4T1 murine mammary carcinoma cells injected into the mammary fat pad of syngeneic BALB/c mice triggered bone lesion formation prior to invasion by cells from the primary tumour and could be abrogated by siRNA knockdown of LOX in the primary tumour cells." (PMID 29098360, 2018). "Additionally, inhibiting LOX can decrease metastasis of human breast cancer-derived tumors in mice." (PMID 28110559, 2017). "Moreover, in breast cancer cells, LOX was found intracellularly, both in the nucleus and cytoplasm, and hydrogen peroxide generated as a side-product upon LOX activity appeared to facilitate cell adhesion and migration through activation of the FAK/Src signaling pathway." (PMID 28425924, 2017). "In addition, LOX expression increases in breast cancer cells under hypoxic conditions." (PMID 29261141, 2017). "Moreover, LOX could also be an interesting target for the development of PET radiotracers for the molecular imaging of its in vivo expression in breast cancer." (PMID 26265048, 2015). "Thus, LOX-PP interaction with CIN85 leads to a decreased invasive phenotype of breast cancer cells." (PMID 24167568, 2013). "During catalytic deamination, LOX generates hydrogen peroxide, a species that can act as a chemoattractant for vascular smooth muscle cells and breast cancer cells, and that also activates FAK and Src; in this way, LOX may be able to indirectly modulate cell adhesion and motility." (PMID 19440335, 2009). "Increased collagen crosslinking by lysyl oxidase (LOX) hardens the extracellular matrix (ECM), promoting breast cancer cell migration and invasion." (PMID 40230452, 2025). "The purpose of this study was to characterise the immunohistochemical expression of LOX and LOXL2 in canine mammary carcinomas and to investigate their prognostic significance." (PMID 41408914, 2025). "LOX and LOXL1-LOXL4 have emerged as potential therapeutic targets for inhibiting breast cancer metastasis." (PMID 39247609, 2024).
breast carcinoma (continued). "In addition to their role in promoting breast cancer cell proliferation and mediating inflammation, breast CAFs deposit collagen type I and fibronectin, secrete matrix metalloproteinases (MMPs), and promote collagen crosslinking (e.g., via lysyl oxidase (LOX))." (PMID 38238542, 2024). "The upregulation of LOX due to chemotherapy in CD8+ T cells has been found to stimulate ECM remodelling in the lungs, thereby facilitating breast cancer metastasis in mice." (PMID 39247609, 2024). "In breast cancer cells, TGF-β activates signalling pathways, such as the Smad3, PI3K, and MAPK pathways, leading to a dose- and time-dependent increase in LOX mRNA expression." (PMID 39247609, 2024). "In breast cancer, ATP7A suppression can impede the function of LOX, a modulator of extracellular matrix (ECM) remodeling, which can consequently lead to tumor cell migration." (PMID 38918694, 2024). "In preclinical models of breast cancer, PMN formation can be prevented by inhibition of P2RY2 signaling or modulation of LOX with β-aminopropionitrile (β-APN), function-blocking antibodies, or LOX-specific RNA interference." (PMID 38129401, 2023). "In terms of targeting the ECM, small molecule inhibitors of lysyl oxidase (LOX) and LOX-blocking antibodies have shown impressive activity in a GEMM of breast cancer." (PMID 38090585, 2023). "LOX promotes the cross-linking of elastin and collagen in the ECM and prevents collagen degradation, which promotes breast cancer progression." (PMID 37916166, 2023). "Extracellular matrix remodeling in the cancer milieu by LOX family members is a well-known function of LOX proteins, and we, therefore, sought to identify the still-unidentified role of upregulated LOXL4 in breast cancer." (PMID 37091157, 2023). "In an orthotopic mouse model of breast cancer, ATP7A silencing attenuated LOX activity and reduced the recruitment of myeloid cells to the lungs, thereby suppressing tumor metastasis." (PMID 37767404, 2023). "In breast cancer, HIF signalling has been demonstrated to result in the secretion of lysyl oxidase (LOX), LOX-like proteins (LOXL2 and 4) and exosomes, which has previously been shown to be crucial in establishing a premetastatic niche in the lungs and bones." (PMID 35646658, 2022). "In order to identify functions unique to LOX in breast cancer cells, we knocked out the five members of the lysyl-oxidase gene family in MDA-MB-231 breast cancer-derived cells." (PMID 36232621, 2022). "For instance, stimulation of CD44 in breast cancer cells was demonstrated to activate Twist expression, thus regulating the EMT phenotype through lysyl oxidase activation." (PMID 35982951, 2022). "The majority of breast cancer metastases are lytic; breast cancer cells produce TNF-A, IL-8, IL-11, IGF1, LIF (leukemia inhibitory factor), lysyl oxidase, RANK ligands, and PTHrP." (PMID 36230523, 2022). "First, in a clinically relevant breast carcinoma model where tumors spontaneously metastasize to the lungs, we demonstrate that combining PTX with the LOX inhibitor BAPN reverses the prometastatic effect of PTX therapy." (PMID 34666995, 2022). "In breast cancer, inhibition of the crosslinking activity of the LOX family with βAPN prevents metastasis in an IDC-type mouse model, showing that LOX proteins promote cancer metastasis by enhanced ECM crosslinking and subsequent stiffness." (PMID 35292774, 2022). "In that sense, LOX and LOXL1-4 are interesting candidates as novel targets to modulate breast cancer progression." (PMID 35800439, 2022). "Lysyl oxidase (LOX), which is known to play a role in enzymatic COL1 cross-linking and fibrils maturation, has been shown to be overexpressed in breast carcinoma and responsible for metastatic niche formation." (PMID 35004699, 2021). "These two LOX/LOXL2 inhibitors reduced the in vitro 2D and 3D proliferation of the breast cancer cell line MDA-MB-231 in a dose-dependent way." (PMID 33669630, 2021).
breast carcinoma (continued). "Next, we analyzed the breast cancer patient data for correlation between OSMR mRNA expression and other lysyl oxidase family members: LOX and LOXL1-4." (PMID 34011405, 2021). "TGFβ has been shown to activate fibroblasts within the tumour microenvironment and therefore induce the production of lysyl oxidase, via SMAD, leading to increased collagen crosslinking and metastasis in breast cancer." (PMID 34283050, 2021). "In this review, we describe LOX enzymes and their role in promoting cancer development and metastases, with a special focus on LOXL2 and breast cancer progression." (PMID 33669630, 2021). "LOX and LOXL2 inhibition have thus been suggested as a promising strategy to prevent metastasis and invasion of breast cancer." (PMID 33669630, 2021). "A previous study reported that LOX cooperates with SNAIL at the protein level to facilitate the EMT and, thus, increases the invasive ability of breast cancer cell lines." (PMID 34202354, 2021). "Among the different LOX enzymes, this review gives particular emphasis to the human LOXL2 (hLOXL2) due to the importance of this particular isoform to breast cancer progression." (PMID 33669630, 2021). "Recent studies indicated that hypoxic mammary tumors secret lysyl oxidase (LOX) to recruit CD11b+ myeloid cell at metastasis sites and these cells produce MMP-2 to disport collagene IV in experimental breast cancer metastasis models." (PMID 33062602, 2020). "Reverse LOX-mediated regulation of EGFR cell surface availability appears to be specific to primary and metastatic breast cancer cell lines." (PMID 32708046, 2020). "We then examined gene expression from 9 different breast cancer datasets and found correlation between HIF1A and LOX, ITGA5, and FN1 mRNAs, supporting the upstream regulatory role of HIF1A in their transcription." (PMID 32415208, 2020). "Lysyl oxidase (LOX), which cross-links collagen fibers and other ECM components and increases tissue stiffness, is upregulated in many cancers including breast cancer and colorectal cancer." (PMID 32645959, 2020). "A previous study showed that TIMP4 secretion was regulated by the expression of LOX/SNAI2 axis and contributed to the malignant phenotype of cancers, e.g., thyroid cancer, colon cancer, and breast cancer." (PMID 31795200, 2019). "By modulating the biological functions of LOX, CCT365623 significantly delayed the development of the primary tumors and suppressed metastatic lung burden in a mouse model of spontaneous breast cancer." (PMID 31130685, 2019). "Pharmacological inhibition of LOX/LOXL2 abrogated the ECM network of CAF and significantly impeded tumor cell migration, like recent findings of CAF-LOXL2 function in breast cancer xenografts and human gastric cancer cell lines." (PMID 31061140, 2019). "Immunoblot assay further confirmed that different breast cancer cells dramatically induced PLOD2 expression in adipocytes, while exerted little effect on LOX protein expression." (PMID 31170987, 2019). "Selected literature references with regards to involvement of lysyl oxidase isoforms LOX and LOXL2 in various kinds of tumors in addition to breast cancer and melanoma." (PMID 29755969, 2018). "Hypoxic LOX, LOXL2, and LOXL4 secretion by breast cancer cells results in collagen remodelling in lungs, which allows the recruitment of bone-marrow derived cells (BMDCs) to the area." (PMID 29362402, 2018). "Beside the action of LOX, crosslinking of collagen by secreted LOXL2 has been shown to contribute to breast cancer progression by promoting integrin signaling via the focal adhesion kinase (FAK)." (PMID 29755969, 2018). "LOX drives the motility of the invasive human ER− Hs578T and human MDA-MB-231 breast cancer cell lines." (PMID 29098360, 2018). "We specifically focus on how copper-binding proteins such as mediator of cell motility 1 (MEMO1), LOX, LOX-like proteins, and secreted protein acidic and rich in cysteine (SPARC) modulate breast cancer from molecular and clinical aspects." (PMID 28425924, 2017).
breast carcinoma (continued). "Like LOX, LOXL2 was shown to promote invasive/metastatic phenotypes in breast cancer cells which was explained by altered LOXL2 protein processing and localization." (PMID 28425924, 2017). "In fact, HIF-1α can overexpress and secrete lysyl oxidase (LOX), lysyl oxidase-like 2 (LOXL2) and LOXL4 in hypoxic breast cancer cells." (PMID 29099748, 2017). "In breast cancer, LOXL4, LOX, and LOXL2, which are expressed in a hypoxia-inducible factor 1-dependent manner, recruit bone marrow-derived cells and facilitate colonization of the lungs." (PMID 28060764, 2017). "In various cancers, the LOX inhibitor and MAO-A inhibitors have been studied for tumor suppression, and these studies are crucial in breast cancer as well." (PMID 29261141, 2017). "Our data show that both LOX and LOXL2 play a significant role in 2D and 3D proliferation of breast cancer cells." (PMID 28199967, 2017). "Regarding LOX/LOXL expression in tumor stromal cells, a recent study with a mouse model of mammary tumor progression showed that LOX expressed by carcinoma-associated fibroblasts stimulates tumor cell intravasation into the vasculature and ensuing metastasis." (PMID 28553358, 2017). "One such example is the enzyme lysyl oxidase (LOX), which is upregulated in bone tropic breast cancer cells." (PMID 27239290, 2016). "High LOX expression induces metastasis in various cancers such as OSCC, CRC, breast cancer, ATC, and lung adenocarcinoma." (PMID 28036074, 2016). "In the present study, we analyzed the Gyorffy dataset to explore the relation between LOX and progression free survival (PFS) in breast cancer patients." (PMID 27147578, 2016). "miR-33b can decrease the levels of MMP-2, MMP-9, LOX, CXCR4, FN and p-FAK in breast cancer cells by regulating downstream targets." (PMID 25919570, 2015). "In contrast, the less metastatic breast cancer cell T47D showed very weak HIF-1α expression and LOX release by hypoxia." (PMID 25238333, 2014). "We showed that the binding of LOX-PP interfered with the CIN85 interaction with c-Cbl, and inhibited the invasive phenotype of MDA-MB-231 and NF639 breast cancer cells." (PMID 24167568, 2013). "Hypoxia has been shown to upregulate LOX expression, via HIF-1α binding to hypoxia responsive elements in LOX promoter, leading to enhanced invasion in an invasive or meta-static breast cancer cell line." (PMID 23545606, 2013). "H/R condition stimulates the LOX-dependent FAK/Src activity, which facilitates breast cancer cell migration through a mechanism mediated by hydrogen peroxide, a by-product of LOX activity." (PMID 22988500, 2012). "Of importance, hydrogen peroxide caused a marked decrease in the levels of phospho-FAK in mesenchymal stem cells, and beta-aminopropionitrile induced inhibition of LOX activation, which is copper dependent, decreased activated FAK in breast cancer cells." (PMID 22276220, 2012). "We found that levels of LOX and COX-2 products of AA are regulated by ACSL4 expression in a breast cancer cell line." (PMID 22808264, 2012). "In summary, the LOX inhibitor, BAPN, was able to significantly decrease the frequency of metastases in animals were challenged by the introduction of large number of breast cancer cells directly into the arterial circulation." (PMID 19440335, 2009). "Lysyl oxidase (LOX), an extracellular matrix remodeling enzyme, appears to have a role in promoting breast cancer cell motility and invasiveness." (PMID 19440335, 2009). "Immunohistochemistry (IHC) depicted elevated levels of LOXL2 in fulvestrant‐resistant breast cancer organoids compared to fulvestrant‐sensitive organoids, with no significant variance in LOX expression." (PMID 40179101, 2025). "The increased expression of lysyl oxidase (LOX) in breast cancer cells facilitates MSC-induced EMT without impacting stemness." (PMID 40676710, 2025).